MAP2K4 (mitogen-activated protein kinase kinase 4)
Description:
Dual specificity protein kinase which acts as an essential component of the MAP kinase signal transduction pathway. Essential component of the stress-activated protein kinase/c-Jun N-terminal kinase (SAP/JNK) signaling pathway. With MAP2K7/MKK7, is the one of the only known kinase to directly activate the stress-activated protein kinase/c-Jun N-terminal kinases MAPK8/JNK1, MAPK9/JNK2 and MAPK10/JNK3. MAP2K4/MKK4 and MAP2K7/MKK7 both activate the JNKs by phosphorylation, but they differ in their preference for the phosphorylation site in the Thr-Pro-Tyr motif. MAP2K4 shows preference for phosphorylation of the Tyr residue and MAP2K7/MKK7 for the Thr residue. The phosphorylation of the Thr residue by MAP2K7/MKK7 seems to be the prerequisite for JNK activation at least in response to pro-inflammatory cytokines, while other stimuli activate both MAP2K4/MKK4 and MAP2K7/MKK7 which synergistically phosphorylate JNKs. MAP2K4 is required for maintaining peripheral lymphoid homeostasis. The MKK/JNK signaling pathway is also involved in mitochondrial death signaling pathway, including the release cytochrome c, leading to apoptosis. Whereas MAP2K7/MKK7 exclusively activates JNKs, MAP2K4/MKK4 additionally activates the p38 MAPKs MAPK11, MAPK12, MAPK13 and MAPK14.
Synonyms: SEK1; SAPKK-1; SAPKK1; JNKK; JNKK1; MEK4; MKK4; PRKMK4; SERK1; SKK1; MAPKK4
Tractability: Small molecule: a structure with a bound ligand is known; a high-quality ligand is known; it has a high-quality binding pocket; it belongs to a druggable protein family. PROTAC: ubiquitination databases record sites on it; its protein half-life has been measured; a small molecule that binds it is known.
Target class: STE protein kinase group; Kinase; Enzyme; Protein Kinase; STE protein kinase STE7 family
Chemical probes: BSJ-04-122 (high quality)
Safety:
Unwanted effects reported when the protein is acted on. In parentheses: how it was acted on, where the effect was seen, and who reports it.
alcoholism (source: ClinPGx)
Gene: Protein-coding gene on chromosome 17 (12,020,828 to 12,143,830, forward strand). Ensembl gene ENSG00000065559.
Subcellular location: Cytoplasm; Nucleus
Subcellular location (Human Protein Atlas): Nucleoplasm; Cell Junctions
Pathways (Reactome):
Immune System: FCERI mediated MAPK activation; JNK (c-Jun kinases) phosphorylation and activation mediated by activated human TAK1; MAP3K8 (TPL2)-dependent MAPK1/3 activation
Cellular responses to stimuli: Oxidative Stress Induced Senescence
Disease: Uptake and function of anthrax toxins
Gene Ontology:
Molecular function: mitogen-activated protein kinase binding; mitogen-activated protein kinase p38 binding; protein binding; JUN kinase kinase activity; protein kinase activity; ATP binding; MAP kinase kinase activity; protein serine kinase activity; protein tyrosine kinase activity
Biological process: cellular response to mechanical stimulus; cellular senescence; Fc-epsilon receptor signaling pathway; JNK cascade; MAPK cascade; signal transduction; cell surface receptor signaling pathway; cellular response to stress; ERBB signaling pathway; intrinsic apoptotic signaling pathway in response to hydrogen peroxide; neuromuscular junction development; smooth muscle cell apoptotic process
Cellular component: cytosol; cytoplasm; nucleus
Genetic constraint (gnomAD): Loss-of-function variants: 2 observed, 29.21 expected, observed/expected ratio (o/e) 0.0685, 90% interval 0.027 to 0.22. The upper end of that interval is the gene's LOEUF score, 0.22, which puts it in group 1 of 6, group 1 being the genes least tolerant of losing a copy. Missense variants: 188 observed, 354.29 expected, observed/expected ratio (o/e) 0.53, 90% interval 0.47 to 0.6. Synonymous variants: 128 observed, 127.14 expected, observed/expected ratio (o/e) 1.01, 90% interval 0.87 to 1.17.
Cancer hallmarks: tumour promoting inflammation (promotes); angiogenesis (promotes); escaping programmed cell death (suppresses); invasion and metastasis (promotes); proliferative signalling (promotes); invasion and metastasis (suppresses); suppression of growth (promotes); escaping immune response to cancer; escaping programmed cell death (promotes)
Homologues: Orthologues: chimpanzee MAP2K4 (100% identical), macaque MAP2K4 (100% identical), pig MAP2K4 (99% identical), rabbit MAP2K4 (99% identical), dog MAP2K4 (98% identical), mouse Map2k4 (98% identical), rat Map2k4 (97% identical), guinea pig MAP2K4 (91% identical), zebrafish map2k4a (86% identical), zebrafish map2k4b (84% identical), tropical clawed frog map2k4 (84% identical), Drosophila melanogaster Mkk4 (57% identical), and 2 more. Paralogues in human: MAP2K7 (44% identical), MAP2K2 (34% identical), MAP2K1 (34% identical), MAP2K5 (33% identical), MAP3K4 (26% identical), MAP3K3 (22% identical), MAP3K2 (21% identical), NEK1 (13% identical).
Diseases named in the same sentence as MAP2K4 in open-access papers:
MAP2K4 is named in the same sentence as 123 diseases in open-access papers, as found by Europe PMC text mining. Sharing a sentence is not in itself a finding about the gene and the disease. The quoted sentences say what the papers report.
breast carcinoma (61 papers, 2005 to 2025). "MKK4 is encoded by MAP2K4 located on chromosomal segment 17p11.2, which can be lost with 7–10% in human epithelial cancers, particularly ovarian and breast cancers, and was therefore initially presumed to be a tumor suppressor." (PMID 37108658, 2023). "In our Asian breast cancer patient data, MAP2K4 had a higher mutation frequency than that seen in Caucasian breast cancer patients." (PMID 35936696, 2022). "It was previously reported that an inactivating mutation in MAP3K1, together with one of its downstream substrates encoded by MAP2K4, was more prevalent in the luminal A subtype of breast cancer." (PMID 32886682, 2020). "Breast cancer cells harboring loss-of-function mutations in MAP2K4 (and MAP3K1) lack JNK-mediated activation of ErbB→CRAF→MEK1/2, and thus, are highly sensitive to MEKi35." (PMID 33122628, 2020). "In line with this, we observed enhanced levels of WNT7B in breast cancer cells with loss-of-function mutations in MAP2K4 and MAP3K1." (PMID 31766464, 2019). "Finally, analysis of 166 estrogen receptor (ER) positive human breast cancer cases showed enhanced levels of WNT7B in breast cancers with loss-of-function mutations in the upstream JNK pathway components MAP2K4 and MAP3K1." (PMID 31766464, 2019). "Indeed, since AKT phosphorylates and inactivates MAP2K4, breast cancer ‘driver’ mutations that activate AKT (e.g. PTEN and PI3K) also cause loss of JNK signaling." (PMID 29856313, 2018). "Whether reduced JNK activity caused by loss of MAP2K4 or MAP3K1 phenocopies the effects of compound JNK deficiency on breast cancer is unclear." (PMID 29856313, 2018). "Of note, inactivating mutations in MAP2K4 have been identified in 5% of breast cancers." (PMID 16457699, 2005). "The prevalence of somatic mutations in MAP2K4 and ARID1A in breast cancer has also been documented in other studies, indicating the presence of a congruent mutational profile within the early-onset Asian breast cancer demographic." (PMID 39482530, 2024). "Regarding breast cancer, astaxanthin increases the activation of metastasis, suppressing mammary serine protease inhibitor, KAI1 (CD82), breast cancer metastasis suppressor 1 and mitogen-activated protein kinase kinase 4 on T47D cells." (PMID 39334719, 2024). "MAP2K4 encodes a member of the MAPK family, and MAP2K4 mutation was identified in breast cancer resistant to AI." (PMID 35804935, 2022). "Focussing on known breast cancer driver genes, we identified clonal mutations in PIK3CA and MAP2K4 in ML10_Abr, and a clonal mutation in FRMPD2 in ML1_Abr." (PMID 35053458, 2022). "The results demonstrated that overexpressed MAP2K4 markedly stimulated cell migration and invasion in breast cancer cells." (PMID 31761784, 2019). "Transiently transfecting with siRNA to inhibit Vimentin expression in MAP2K4-overexpressing breast cancer cells reduced cell proliferation by MTT and EdU incorporation assays as well as inhibited G1 to S cell-cycle transition." (PMID 31761784, 2019). "Contradictory research results have heightened interest in discovering the precise role, specific functions, and mechanisms of MAP2K4 in the development of breast cancer." (PMID 31761784, 2019). "In this study, we first investigated the oncogenic role of MAP2K4 breast cancer, then we found that MAP2K4 overexpression upregulated p-PI3K and p-AKT." (PMID 31761784, 2019).
breast carcinoma (continued). "Based on these findings, we supposed that MAP2K4 promotes migration and invasion of breast cancer cells by interacting with Vimentin." (PMID 31761784, 2019). "Correlation between the clinicopathologic characteristics and MAP2K4 and Vimentin co-expression patterns in breast cancer." (PMID 31761784, 2019). "The Spearman’s test showed that MAP2K4 expression was positively correlated with Vimentin expression in the breast cancer patients (γ=0.753, P<0.001)." (PMID 31761784, 2019). "In this study, we started by overexpressing MAP2K4 in breast cancer cells to reveal the biologic functions of MAP2K4 in breast cancer and showed that MAP2K4 promoted cell proliferation, migration, and invasion in vitro and in vivo." (PMID 31761784, 2019). "Here, we further explored MAP2K4 biological functions in the regulation of breast cancer signaling pathways." (PMID 31761784, 2019). "To explore the clinical prognostic value of MAP2K4 in breast cancer, we examined MAP2K4 and Vimentin expression levels in breast cancer tissues and analyzed the correlations between the expression of these markers and the clinicopathologic parameters." (PMID 31761784, 2019). "According to our study, overexpressed MAP2K4 in breast cancer cells increased proliferation, migration, and invasion in vivo and in vitro, while MAP2K4 knockdown restored the effects." (PMID 31761784, 2019). "In our study, MAP2K4 and Vimentin co-expression is confirmed to be an unfavorable factor in breast cancer." (PMID 31761784, 2019). "Based on the invasion and migration assay results, we examined EMT signals in MAP2K4-overexpressing breast cancer cells and observed that N-cadherin, Vimentin, and Slug were significantly elevated while E-cadherin was decreased, as we expected." (PMID 31761784, 2019). "The MAP2K4 mutant breast cancer cells were also sensitive to the MEK inhibitor trametinib and the ERK inhibitor SCH772984." (PMID 29795445, 2018). "For example, loss‐of‐function mutations in MAP3K1 and MAP2K4, two kinases involved in activation of JNK, are most commonly found in luminal breast cancer of which approximately 15% contain mutations in either gene." (PMID 30190333, 2018). "MAP3K1 acts upstream of MAP2K4 in signaling and in the METABRIC breast cancer study, loss-of-function mutations in these genes is mutually exclusive (p < 0.001)." (PMID 29795445, 2018). "Loss-of-function mutations in the JNK signaling pathway (e.g. MAP3K1, MAP2K4, and MAP2K7) are implicated in the etiology of breast cancer." (PMID 29856313, 2018). "This is a significant finding because frequent mutational inactivation of genes that encode JNK pathway components (e.g. MAP2K4 and MAP3K1) are detected in human breast cancer." (PMID 29856313, 2018). "An important goal for future studies will be to directly test the effect of MAP2K4 and MAP3K1 gene mutation on breast cancer." (PMID 29856313, 2018). "The frequent mutation of the JNK pathway in human breast cancer (including the genes MAP3K1, MAP2K4, and MAP2K7) implicates reduced JNK signaling in the etiology of mammary carcinoma." (PMID 29856313, 2018). "MAP2K4 amplifications are well recognized in breast tumors, but until now were mainly found in the group of luminal mammary cancers." (PMID 25296970, 2014). "For example, users can infer the differential gene expression and survival impact of MAP2K4 differential gene expression in breast cancer using information from TCGA and GSE7390." (PMID 23418540, 2013). "Amplification was observed over cancer genes previously implicated in breast cancer development including ERBB2, CCND1, MYC, MDM2, ZNF217, and ZNF703 and a homozygous deletion involving MAP2K4 was identified." (PMID 22608084, 2012).
breast carcinoma (continued). "Vimentin’s interaction with mitogen-activated protein kinase kinase 4 (MAP2K4) propagates the effect of MAP2K4 on promoting breast cancer cell proliferation, migration, and invasion by activating the PI3K/AKT pathway, the downstream proteins such as c-JUN, the G1/S cell cycle, and the EMT." (PMID 40229242, 2025). "Finally, our results in Breast-AdenoCA also highlighted some genes that are specifically known to be frequently mutated in breast cancer, including PIK3CA, CDH1, GATA3, and MAP2K4." (PMID 38062391, 2023). "In summary, MAP2K4 activates the phosphorylated PI3K/AKT signaling pathway to activate downstream cycle-associated proteins and EMT signals, which promotes cell proliferation, migration, and invasion in breast cancer." (PMID 31761784, 2019). "On this topic, we confirmed a new mechanism for MAP2K4 in breast cancer." (PMID 31761784, 2019). "Furthermore, we also reported that increased MAP2K4 expression was a favorable prognostic factor in breast cancer." (PMID 31761784, 2019). "To confirm that MAP2K4 does affect the proliferation, migration, and invasion of breast cancer cells, in vitro, we transiently transfected two siRNA sequences to knockdown MAP2K4 expression in breast cancer cells." (PMID 31761784, 2019). "Furthermore, inhibiting p-PI3K expression using its specific inhibitor can reverse phenotypic changes in MAP2K4-overexpression breast cancer cells." (PMID 31761784, 2019). "Finally, we observed that knocking down Vimentin suppressed p-PI3K, p-AKT, c-JUN, c-Myc, and Cyclin D1(CCND1), N-cadherin and restored E-cadherin expression in MAP2K4-overexpressed breast cancer cells." (PMID 31761784, 2019). "In a breast cancer pilot study, MAP2K4 was recognized to be a candidate tumor suppressor." (PMID 31761784, 2019). "Moreover, two out of ten previously identified oncogenic point mutations that did not result in exon skipping events were also PAC detected in our cohort of breast cancer cell lines: MAP2K4 c.551C>G in MDA-MB-134VI and PTEN c.274G>C in CAMA-1;." (PMID 18688287, 2007). "Moreover, MAP2K4 interacts with Vimentin further accelerating cell proliferation, migration, and invasion, and co-expression of MAP2K4 and Vimentin was found to be an unfavorable factor in breast cancer prognosis." (PMID 31761784, 2019). "Therefore, we strongly speculate that MAP2K4 has an oncogenic role in breast cancer, which is at odds with a previous study." (PMID 31761784, 2019). "However, the pathway by which MAP2K4 promotes breast cancer remained undefined." (PMID 31761784, 2019). "In breast cancer cells, MAP3K1 activates MEK1/2 indirectly by stimulating an MAP2K4/MAP2K7→JNK pathway, which results in JNK-mediated positive feedback activation of ERBB RTKs that activate MEK1/235." (PMID 33122628, 2020). "Regarding the mechanism of action, our study also was the first to show that MAP2K4 overexpression activates the PI3K/AKT pathway and interacts with Vimentin in breast cancer cells." (PMID 31761784, 2019). "MDA-MB-468 breast cancer, H358 lung cancer and HCT116 colon cancer cells in which MAP3K1 or MAP2K4 was knocked out all show a marked increase in sensitivity to selumetinib." (PMID 29795445, 2018).
breast carcinoma (continued). "Deletions of functional copies of MAP2K4 and BRCA1 have also been reported in several breast cancer cell lines." (PMID 25264427, 2014). "For example, RAR-L3 (8p21.2) and RAR-L5 (17p12), where PPP2R2A and MAP2K4 are located, respectively, and RAR-G13 (17q12), where ERBB2 is located, were consistently detected in a recent large-scale breast cancer genetic subgroup study." (PMID 22938721, 2012). "Indeed, vimentin has been described to interact with MAP2K4 to activate AKT pathway, leading to increased proliferation and invasion of breast cancer cells." (PMID 34203746, 2021). "In addition to these passenger mutations, we find SV events involving mobile elements that disrupt the coding sequence of known (MAP2K4) and suspected (YTHDF2) driver genes in breast cancer." (PMID 34158539, 2021). "Although MAP2K4 was reported in some tumors, its specific function and mechanism in breast cancer have not been clarified, and further investigation is needed." (PMID 31761784, 2019). "Re-expression of MAP2K4 in MAP2K4 mutant MPE600 breast cancer cells was not compatible with proliferation, consistent with the tumor suppressor nature of this gene." (PMID 29795445, 2018). "However, specific function and mechanism of MAP2K4 in breast cancer have not been clarified." (PMID 31761784, 2019). "However, in basal‐like breast cancer, mutations in MAP3K1 or MAP2K4 are notably absent, suggesting that they may not provide similar increase in cellular fitness to what is observed in luminal breast cancer cells." (PMID 30190333, 2018). "Note that in the time course experiment using four breast cancer cell lines, the MEK inhibitor sensitivity of the two MAP2K4 mutant breast cancer cell lines was also not very apparent during the first 72 h of culture and similar result was seen in the isogenic MAP3K1 and MAP2K4 knockout cells." (PMID 29795445, 2018).